SLC22A5 (solute carrier family 22 member 5)
Diseases named in the same sentence as SLC22A5 in open-access papers (continued):
Sharing a sentence is not in itself a finding about the gene and the disease.
carnitine deficiency (continued). "Primary carnitine deficiency (PCD, OMIM #212,140) is a rare inherited autosomal recessive disorder of fatty acid oxidation caused by mutations of the solute carrier family 22 member 5 (SLC22A5, MIM:603,377) gene." (PMID 38961493, 2024). "Systemic carnitine deficiency is an autosomal recessive disease caused by homozygous or compound heterozygous mutations in the solute carrier family 22 member 5 gene (SLC22A5), which encodes the organic cation/carnitine transporter 2 (OCTN2)." (PMID 37239314, 2023). "Large deletions and duplications of the SLC22A5 gene, while not a common mechanism causing systemic carnitine deficiency, have been identified in at least one individual with this diagnosis." (PMID 37239314, 2023). "Primary carnitine deficiency (PCD, OMIM 212140) refers to an autosomal recessive disorder of fatty acid oxidation caused by mutations in the SLC22A5 gene, which encodes the organic cation transporter 2 (OCTN2)." (PMID 36568374, 2022). "Defects in OCTN2, due to autosomal recessive mutations in the SLC22A5 gene, result in carnitine deficiency, as a consequence of reduced carnitine transport and intracellular accumulation, increased urine excretion of carnitine and decreased serum levels of carnitine." (PMID 32370025, 2020). "We Sanger sequenced the 5′ untranslated region (UTR) of SLC22A5 in individuals with possible primary carnitine deficiency in whom no or only one mutant allele had been found." (PMID 31187905, 2019). "Methylmalonic acidemia, phenylketonuria, and primary carnitine deficiency were the major IEMs and the mutations in PAH, SLC22A5, and MMACHC genes are the leading causes of IEMs resulting in phenylketonuria, primary carnitine deficiency, and methylmalonic acidemia, respectively, in Jining area." (PMID 29731766, 2018). "Primary Carnitine Deficiency (PCD) is characterized by a low concentration of plasma and tissue carnitine due to recessive mutations in Solute Carrier Family 22 Member 5 (SLC22A5) gene which encodes Organic Cation/Carnitine Transporter 2 (OCTN2)." (PMID 30477112, 2018). "Primary carnitine deficiency (PCD, OMIM #212140) is an autosomal recessive carnitine transport defect caused by biallelic pathogenic variants in the solute carrier family 22 member 5 (SLC22A5) gene, which encodes organic cation/carnitine transporter type 2 (OCTN2)." (PMID 38125748, 2023). "Moreover, four cases of primary carnitine deficiency had mutations in the SLC22A5 gene while no genetic mutation was detected in one primary carnitine deficiency case." (PMID 29731766, 2018). "Systemic primary carnitine deficiency (SPCD) is a progressive autosomal disturbance connected with impaired carnitine uptake by plasmatic membranes because of a deficiency in the OCTN2 transporter, which is coded by the SLC22A5 gene (localized on the 5q31 chromosome)." (PMID 33805796, 2021).
Crohn disease (20 papers, 2006 to 2022). A gastrointestinal disorder characterized by chronic inflammation involving all layers of the intestinal wall, noncaseating granulomas affecting the intestinal wall and regional lymph nodes, and transmural fibrosis. "This theory is supported by the findings that, mutations in SLC22A5 (OCTN2), which encodes a carnitine transporter, are associated with Crohn’s disease, with carnitine essential for fatty acid oxidation." (PMID 29515999, 2018). "These include disease-associated variants (e.g., an eQTL for SLC22A5 associated with Crohn’s disease and a sQTL for GSDMB associated with a range of autoimmune diseases)." (PMID 27863252, 2016). "Carnitine’s role in the GI tract has recently been highlighted by several publications linking mutations in genes encoding carnitine transporters OCTN1 (SLC22A4) and OCTN2 (SLC22A5) with Crohn’s disease." (PMID 25757041, 2015). "Carnitine’s role in the GI tract has recently been highlighted by several publications linking mutations in genes encoding carnitine transporters OCTN1 (SLC22A4) and OCTN2 (SLC22A5) with Crohn’s disease (CD)." (PMID 23112839, 2012). "Carnitine’s role in the GI tract has recently been highlighted when several reports linked mutations in genes encoding carnitine transporters OCTN1 (SLC22A4) and OCTN2 (SLC22A5) with Crohn’s disease (CD)." (PMID 23112839, 2012). "Functional variants of SLC22A4 and SLC22A5 ion transporter genes that alter their transcription and transporter functions are associated with the Crohn's disease IBD5 locus." (PMID 19898610, 2009). "The chromosomal region 5q31 contains several genes involved in immune and inflammatory responses and the SLC22A4 and SLC22A5 genes were associated with two autoimmune diseases (rheumatoid arthritis and Crohn's disease)." (PMID 16796743, 2006). "Recent reports performed associations of some polymorphisms within the SLC22A4 and SLC22A5 genes with two other autoimmune complex diseases (rheumatoid arthritis and Crohn's disease)." (PMID 16796743, 2006). "Polymorphisms in the carnitine transporters, encoded by the SLC22A4 and SLC22A5 genes, have been involved in susceptibility to two other autoimmune diseases, rheumatoid arthritis and Crohn's disease." (PMID 16796743, 2006). "The carnitine transporter OCTN2 (SLC22A5), required for cellular uptake of carnitine, has been identified in a susceptibility locus for IBD, and the susceptibility variant has been associated with decreased levels of SLC22A5 transcripts in Crohn’s disease." (PMID 35805947, 2022). "Carnitine transporter mutations in Crohn's disease consists of missense mutation(s) in the gene coding plasma membrane transporter OCTN1 (SLC22A4) and/or mutation(s) in the promoter of the gene encoding OCTN2 (SLC22A5)." (PMID 20398344, 2010). "The OCTN2-promoter (rs2631367) is a transversion (-207G>C) disrupting a heat shock element in the promoter region of the SLC22A5 gene and it has been described, together with L503F, as etiologic variant in Crohn disease." (PMID 16796743, 2006). "At a false discovery rate (FDR) of 5%, we observed a significant enrichment of SLC22A4, SLC22A5, and P4HA2 genes for Crohn’s disease and inflammatory bowel disease (IBD)." (PMID 26053627, 2015).
cardiomyopathy (19 papers, 2012 to 2025). A disease of the heart muscle or myocardium proper. "Another study suggested that heterozygosity for SLC22A5 variants is less likely to be an important cause of cardiomyopathy." (PMID 31500110, 2019). "In males, this can be demonstrated with a mutation in SLC22A5 that causes both cardiomyopathy and male infertility due to altered ability to break down lipids." (PMID 28640878, 2017). "Studies have shown that R245X and V295X mutations in SLC22A5 may be associated with cardiomyopathy, which may be the only clinical phenotype." (PMID 37351314, 2023). "In this study, 324 individuals with cardiomyopathy were tested for SLC22A5 variants." (PMID 31500110, 2019). "SLC22A5 gene encodes for the plasmalemmal carnitine transporter and the related disease encompasses a broad clinical spectrum including metabolic decompensation, cardiomyopathy, hypoglycemic hypoketotic encephalopathy or absence of symptoms." (PMID 38849547, 2024).
asthma (13 papers, 2010 to 2025). "For example, genetic mutations in SLC22A5 have been associated with asthma susceptibility and SLC22A5 expression, which can lead to reduced carnitine transport, impacting energy metabolism, and potentially enhancing inflammatory responses in the airways." (PMID 39100210, 2024). "SLC22A5 was remarkably reduced in patients with severe asthma and has been associated with carnitine and central energy metabolism dysregulation in asthma." (PMID 39100210, 2024). "Single nucleotide polymorphisms (SNPs) in the SLC22A5 gene, which encodes OCTN2, have consistently been associated with asthma and other inflammatory diseases and in vitro results implicate an upregulation of OCTN2 expression by aeroallergens." (PMID 31394757, 2019). "SLC22A5 and SLC30A8 are critically involved in asthma-related airway inflammation and immune cell function, with SLC22A5 also mediating drug absorption mechanisms in bronchial epithelial cells." (PMID 41425581, 2025). "It has been confirmed that prednisolone (a drug commonly for asthma) with L-carnitine ester stimulate prednisolone absorption across the bronchial epithelial cells via a SLC22A5 mechanism." (PMID 30239845, 2019). "Two large-scale GWAS for asthma found that SLC22A5 and SLC30A8 were significantly associated with asthma." (PMID 30239845, 2019). "Asthma is a disease with demonstrated heritability in humans, and several genes, including the IKZF3-ZPBP2-GSDMB-ORMDL3 locus, HLA-DQ, IL1RL1, IL33, TSLP, SLC22A5, SMAD3, and RORA have been consistently associated with asthma in genome-wide association studies (GWAS)." (PMID 23984888, 2013). "There were 8 of 11 genes (8/11 = 72.7%) showing significantly different expression profiles between severe asthma and controls; for example, GNGT2, TLR6, TTC19, LNPEP, SLC22A5 and HLA-DQA1." (PMID 33066754, 2020).
breast carcinoma (11 papers, 2016 to 2025). "Another transporter involved in the proliferation associated with specific metabolic changes of ER-positive breast cancer cells is the solute carrier family 22 member 5 (SLC22A5), which encodes an organic cation/carnitine transporter (also called OCTN2)." (PMID 29865240, 2018). "Finally, SLC22A5, implicated in pancreatic and breast cancers, may contribute to LUAD progression through metabolic regulation." (PMID 40722386, 2025). "An analysis with the use of CANCERTOOL revealed that SLC22A5 expression was significantly lower in colorectal cancer than in normal tissue, which was also the case in the breast cancer." (PMID 31861504, 2019). "By applying to the exome and RNA sequencing data of 78 normal-paired breast cancer samples we collected from 1998 to 2008, our approach identifies five driver mutations in ADPGK, NUP93, PCGF6, PKP2 and SLC22A5 genes." (PMID 27625789, 2016). "Interestingly, a prognosis for breast cancer is better during the first 7 years for patients with a high SLC22A5 expression level; after this period, it is the other way round and a prognosis is much better in case of patients with a low expression level." (PMID 31861504, 2019). "ER has been shown to be involved in transcriptional regulation of many proteins including also SLC family members, for example, OCTN2 (SLC22A5), a poly‐specific organic cation transporter also expressed in kidneys, which was shown to be regulated by ER in breast cancer cells." (PMID 31724834, 2019). "Expression of SLC22A5 is regulated by estrogens, and an estrogen receptor responsive element was found in its first intron —an interesting observation bearing in mind the role of estrogen signaling in breast cancer." (PMID 31861504, 2019). "However, the dataset with breast cancer patients’ gene expression data collected with Affymetrix gene chip showed a prognosis for overall survival was significantly better for patients with high expression level of SLC22A5." (PMID 31861504, 2019). "This might mean that patients with breast cancer that have reached a certain threshold of SLC22A5 expression have a better prognosis regardless of ER status." (PMID 31861504, 2019).
glioblastoma (10 papers, 2019 to 2025). The most malignant astrocytic tumor (WHO grade IV). "Cells of the T98G glioblastoma multiforme cell line have also shown robust expression of OCTN2/SLC22A5." (PMID 36770817, 2023). "The potential side effects of inhibiting SLC22A5 to treat glioblastoma must of course be taken into consideration and evaluated." (PMID 32362913, 2020). "Moreover, a high expression of OCTN2/SLC22A5 was detected in ER-positive breast cancer (on mRNA levels) and glioblastoma (on mRNA and protein levels)." (PMID 36839686, 2023).
colorectal cancer (8 papers, 2008 to 2025). A primary or metastatic malignant neoplasm that affects the colon or rectum. "An expression quantitative trait locus-based analysis revealed that a mutation rs27437, residing in the upstream of SLC22A5, can affect colorectal cancer risk by regulating SLC22A5 expression." (PMID 30627228, 2018). "Significantly decreased levels of SLC22A5 have been reported in colorectal cancer tissues compared to normal tissues in eQTL studies." (PMID 34234117, 2021).
glioma (7 papers, 2019 to 2024). A benign or malignant brain and spinal cord tumor that arises from glial cells (astrocytes, oligodendrocytes, ependymal cells). "Inhibition or overexpression of SLC22A5 in vitro was shown to reduce the survival of glioma cells through FAO modulation." (PMID 37298344, 2023). "Glioma cell survival was additionally affected either by silencing or upregulation of SLC22A5 levels in an FAO-dependent manner." (PMID 37298344, 2023). "Finally, glioma cell survival has been shown to be heavily dependent on both fatty acid oxidation (FAO) and SLC22A5 activity because carnitine, which is required for FAO, is delivered to the cell by SLC22A5, which is upregulated in gliomas." (PMID 37298344, 2023). "SLC22A5 expression was shown to be upregulated in glioma cells, and its plasma membrane levels varied, with different SLC22A5 expression levels revealing a correlation between the rate of fatty acid oxidation (FAO) and the transporter level, as well as the carnitine transport." (PMID 37298344, 2023). "Interestingly, SLC22A5 has been recently reported to be critical for the survival of glioma cells, supporting increased fatty acid metabolism, which is possibly mirrored in our positive correlation with [18F]FPIA uptake." (PMID 34356874, 2021). "In agreement, the combination of a chemotherapeutic agent inhibiting carnitine uptake transported by SLC22A5, along with the CPT1 inhibitor etomoxir, exhibited a synergistic effect with a more robust inhibition of FAO, decreasing survival and enhancing glioma cell death." (PMID 37298344, 2023). "Finally, to establish whether LAC transport into U87MG cells limited its ability to contribute to intracellular acetyl-CoA pools, the carnitine importer SLC22A5/OCTN2, which is also believed to transport LAC, was overexpressed in this glioma cell line." (PMID 36587768, 2023). "Additionally, a therapeutic approach targeting both SLC22A5 and carnitine palmitoylotransferase 1 (CPT1), which mediates the formation of acylcarnitine from L-carnitine required for FAO, was demonstrated to reduce glioma cell proliferation and provoke persistent apoptosis." (PMID 37298344, 2023).
Skeletal myopathy (4 papers, 2016 to 2024). "Members of the SLC22 transporter family, such as SLC22A5, play important roles in carnitine transport and mutation in SLC22A5 has been implicated in systemic carnitine deficiency related cardiomyopathy, skeletal myopathy and metabolic abnormalities." (PMID 34233735, 2021).
type 1 diabetes (4 papers, 2006 to 2022). "The purpose of this study was to investigate the influence of the SLC22A4 and SLC22A5 genes in type 1 diabetes risk in the Spanish population." (PMID 16796743, 2006). "We tested six polymorphisms in the SLC22A4 and SLC22A5 genes and in five of them no significant independent association with type 1 diabetes could be found." (PMID 16796743, 2006).
attention deficit-hyperactivity disorder (3 papers, 2018 to 2020). A disorder characterized by a marked pattern of inattention and/or hyperactivity-impulsivity that is inconsistent with developmental level and clearly interferes with functioning in at least two settings (e.g. at home and at school). "CPT1, CPT2, and the carnitine transporter SLC22A5/OCTN2 are expressed in several regions of rat brain; in addition, a deletion in the OCTN2 gene has been associated with attention-deficit/hyperactivity disorder, and mutations in the HTML gene were considered to be a risk factor in autism." (PMID 33371457, 2020). "In addition, OCTN2 appears to be essential for the functioning of the brain; a deletion in SLC22A5 was reported in the attention deficit/hyperactivity disorder, and the deficiency of carnitine biosynthesis was revealed to be a risk factor in autism with improvement after carnitine supplementation." (PMID 31861504, 2019).
Systemic primary carnitine deficiency (3 papers, 2019 to 2024). "Additional potential targets for chaperoning attempts in the SLC22 family are mutated OCTN2 transporters (SLC22A5; organic cation/carnitine transporter), causing primary systemic carnitine deficiency (CDSP)." (PMID 36611832, 2022).
Arrhythmia (2 papers, 2020 to 2021). Any cardiac rhythm other than the normal sinus rhythm. "When the 90 node genes were compared with the arrhythmia-related targets, 40 (95.2% of 42) overlapping genes were assigned, with the other two non-overlapping genes being SLC22A5 and ECHS1." (PMID 35004871, 2021).
colitis (2 papers, 2021 to 2025). Inflammation of the colon. "Moreover, polymorphisms in SLC22A5, encoding the carnitine transporter OCTN2, are a genetic risk factor for IBD, and its deletion in mice results in colitis." (PMID 40723826, 2025).
dilated cardiomyopathies (2 papers, 2015 to 2023). "The variants in VCL, SLC22A5, and FHOD3 have been shown earlier to be associated with HCM or dilated cardiomyopathies (DCM)." (PMID 37342443, 2023).
type 2 diabetes (2 papers, 2006 to 2020). "Additional studies in independent populations and in both type 1 and type 2 diabetes patients will be needed to confirm the putative influence of the SLC22A4 and SLC22A5 genes in these diseases." (PMID 16796743, 2006).
celiac disease (1 paper, 2020). An autoimmune genetic disorder with an unknown pattern of inheritance that primarily affects the digestive tract. "Of note, the human homologs of four of the CD11b+ DC Runx3 targets, CD300LF, IFIH1, IRF4 and SLC22A5 (mouse Slc22a21) harbored SNPs associated with IBD, CD, UC and/or celiac disease and the two former genes are common Runx3 targets in RM and CD11b+ DC." (PMID 32453801, 2020). "Ten of these cDC2 high-confidence Runx3 targets were common to those in RM and human homologs of four, CD300LF, IFIH1, IRF4 and SLC22A5 (mouse Slc22a21) harbored SNPs associated with IBD, CD, UC and/or celiac disease." (PMID 32453801, 2020).
citrin deficiency (1 paper, 2013). "Three mutations in the SLC25A13 gene (for citrin deficiency) and one mutation in the SLC22A5 gene (for CUD) were analyzed in newborns who demonstrated an inconclusive primary screening result (with levels between the screening and diagnostic cutoffs)." (PMID 23394329, 2013).
endometrial cancer (1 paper, 2019). Primary or metastatic malignant neoplasm involving the endometrium (mucous membrane that lines the endometrial cavity). "The prognosis of overall survival correlated with SLC22A5 expression was either favorable or unfavorable, depending on the type of cancer, with the biggest impact on patients’ prognosis in pancreatic, renal and endometrial cancer." (PMID 31861504, 2019).
fatty acid metabolic disorders (1 paper, 2025). "PCD is one of fatty acid metabolic disorders caused by mutations in the gene for the high-affinity carnitine transporter carnitine transporter protein (SLC22A5) on cell membranes." (PMID 40727585, 2025).